IL6 (interleukin 6)
Diseases named in the same sentence as IL6 in open-access papers (continued):
Sharing a sentence is not in itself a finding about the gene and the disease.
prostate carcinoma (continued). "Similar results for Pyk2 and FAK have been observed in different cell types (hemopoietic cancer cells, ovarian cancer cells, smooth vascular cells, and prostate cancer cells) following treatment with SDF-1α, IL-6, EGF, IL-8, and PDGFβ." (PMID 34944779, 2021). "Reciprocally, M2 macrophages promote the transformation of normal fibroblasts into CAFs via IL-6 and SDF-1 in prostate cancer." (PMID 34858425, 2021). "SEVs secreted from prostate cancer cells under hypoxic condition delivered more signaling factors than normal oxygen condition, including TGF‐β, TNF‐α, and IL‐6, thereby promoting cell invasion by altering the tumor microenvironment." (PMID 33508878, 2021). "It was also observed that both IGF-1 and IL-6 can induce the phosphorylation of AKT at Ser-473 and PKCα at Ser-657 in prostate cancer cells in the present study." (PMID 34682865, 2021). "It was further shown that bFGF triggers IL-6 and prostate-specific membrane antigen (PSMA) expression, markers of chronic inflammation and prostate cancer prostate cancer progression in advanced stages." (PMID 33804681, 2021). "For example, within TMEs of breast and prostate cancers, it was observed that the expression levels of angiogenic factors such as vascular endothelial growth factor (VEGF) and Interleukin 6 (IL-6) are upregulated by the MSCs." (PMID 34789315, 2021). "Studies reported that prostate cancer cells can directly produce pro‐osteoclastogenic factors including RANKL and IL‐6." (PMID 33659051, 2021). "In vitro or in vivo models demonstrated that IL6, IL8, and CXCL16 can promote prostate cancer growth or metastasis." (PMID 34638448, 2021). "Various survival pathways have been reported to participate in prostate cancer growth in the bone niche, including PTHrP, TGF-β, IGF-1, FGF-2, IL-6 as well as ET-1 signaling." (PMID 34831167, 2021). "Co-cultures of macrophages with prostate cancer cell lines were shown to activate BMP-6/IL-6 loop, where BMP-6 secreted by prostate cancer cells induced expression of IL-6 in macrophages." (PMID 33572108, 2021). "Collectively, our results illustrate that MALT1 modulates the expressions of IL-6 and CXCL5 via NF-κB activation, thereby contributing to tumor progression and malignancy in prostate carcinoma cells." (PMID 33802402, 2021). "Recently, accumulating evidence indicated that IL-6 is indispensable for activation of JAK/STAT pathway, which is involved in the oncogenesis of prostate cancer." (PMID 34630112, 2021). "IL-6 can activate an IL-6R/STAT3/miR-34a feedback loop in colorectal, breast and prostate cancer cells and it has been demonstrated that miR-34 repression is required for IL-6-induced EMT and invasion." (PMID 34361105, 2021). "It was established that IL-6 is elevated in tissues of BPH and prostate carcinomas in men74 and intratumoral IL-1β levels significantly correlate with biochemical recurrence in prostate cancer patients." (PMID 33772116, 2021). "Activated osteoblasts also produce factors that trigger prostate cancer cell proliferation (e.g., VEGF, C-C motif chemokine ligand CCL2, IL-6 and IL-8)." (PMID 34831167, 2021). "In prostate cancer, BMP-6 produced by neoplastic cells acts on adjacent macrophages and activates NF-κB and SMAD1 signaling to increase IL-1α and IL-6 secretion." (PMID 33842333, 2021). "Compounds 1 and 2 were shown to potently inhibit the production of cytokines IL-6 and 8, which are autocrine growth factors that play a key role in inducing the development of hyperplasia of the prostate in BPH patients and in prostate cancer cells." (PMID 34204056, 2021). "In the prostate cancer cells DU145, blocking of autocrine IL-6 restored the ability of cells to induce type IFN expression in response to cGAMP." (PMID 33790360, 2021). "Suppression of JAK1/2 by AZD1480 also inhibited progression of CRPC 37 and reduced IL6‐induced metastases, suggesting that JAK signalling is activated in prostate cancer." (PMID 34322995, 2021).
prostate carcinoma (continued). "In keeping with the high abundance of IL-6 and TGF-β in prostate cancer cells’ secretome, conditioned media from DU-145 cells also upregulate both CB1 and CB2 expression in treated HPFs." (PMID 31991773, 2020). "During the early phase of metastasis, cytokines such as TGFβ, IL-6, CXCL8, IL-7, CXCL16, and CX3CL1 induce EMT in prostate cancer cells and transforms them to exhibit higher migratory and invasive potentials." (PMID 32585812, 2020). "RNA sequencing data shows an upregulation of immunogenic chemokines and cytokines (CXCL, CSF2, IL6, and TNF) in human prostate cancer cells (PC3, PC3M) and Luminex-assayed cytokine response in mice treated with CRC2631." (PMID 33216833, 2020). "In prostate cancer, paracrine IL-6/JAK2/STAT3 stimulates the autocrine IL-6 loop, and IGF-IR activation induced by both IL-6 and IGF enhances EMT through induction of the STAT3/NANOG/Slug axis." (PMID 31952344, 2020). "Results of this study are similar to other previous studies which demonstrated that HO-1 downregulated IL-6 expression in microglial BV2 cells, macrophages RAW264.7 cells, and prostate carcinoma PC-3 cells." (PMID 32204510, 2020). "Furthermore, other reports suggest that IL-6 may be one of the key factors contributing to increased tumoral growth in the absence of androgens and as such, IL-6 could be an oncogenic factor in PCa and a regulator of prostate cancer progression." (PMID 32610428, 2020). "In prostate cancer, CD44 expression significantly correlates with IL-6, a STAT3-activating cytokine, and IL-6 or STAT3 inhibition both decrease CD44 and EMT-related protein levels in cancer cell lines." (PMID 33335857, 2020). "Next, we examined the effect of IL-6, IL-8, CCL5, and FGF2 in the regulation of ERG expression by adding them to the culture media of prostate cancer cells, respectively." (PMID 33425737, 2020). "The IL6/STAT3/miR-34a feedback loop appears essential for EMT, invasion, and metastasis of colorectal, breast, and prostate cancer cells." (PMID 33322216, 2020). "PPAR gamma is a known suppressor of the interleukin 6 (IL-6)/STAT3 pathway, and prostate cancer progression positively correlates with STAT3 phosphorylation." (PMID 33182324, 2020). "Akt is downstream of JAK in the IL-6/PI3K/Akt pathway, and this pathway has been shown to promote prostate cancer cell survival." (PMID 32528731, 2020). "Thus, whereas hPCL3S seemed to be somehow implicated in the regulation of IL6 expression, the mechanism is independent of the activation of the Wnt/β-catenin pathway in prostate cancer cells and might thus involve another cell-specific signaling pathway." (PMID 32256978, 2020). "When blocking IL-6 using antibody or STAT3 inhibition, the expression levels of CD44 and EMT-related proteins in prostate cancer cells were significantly attenuated both in vitro and in vivo." (PMID 31315262, 2019). "We used human and murine prostate cancer cell lines to examine the role of tumor burden in tumor aggressiveness, as well as its correlation with cancer stem cell (CSC) marker levels and IL-6 signaling." (PMID 31315262, 2019). "Our previous data showed that IL-6 was significantly correlated with tumor aggressiveness and the transition to CRPC of prostate cancer." (PMID 31315262, 2019). "In prostate carcinoma cells, MIEN1 provoked Akt phosphorylation; moreover, MIEN1 downregulated N-myc downstream regulated 1 (NDRG1) but upregulated interleukin-6 (IL-6) gene expression." (PMID 31581708, 2019).
prostate carcinoma (continued). "Accordingly, we further identified a role for IL-6 in CD44 expression, CSC-like properties, and the TME in prostate cancer." (PMID 31315262, 2019). "Previously, we showed that the IL-6 level is significantly correlated with tumor aggressiveness and the transition of CRPC to prostate cancer." (PMID 31315262, 2019). "Birnie and colleagues identified genes with altered expression in prostate cancer stem cell population such as NFKB1 and IL6." (PMID 31083587, 2019). "It has been suggested that both IL-6 and NDRG1 are modulated by Akt signal pathways; however, no report has yet studied the correlations among MIEN1, Akt, IL-6, and NDRG1 in human prostate cancer." (PMID 31581708, 2019). "We previously reported that altered IL-6/STAT3 signaling is important for CRPC transition and aggressive behavior in prostate cancer." (PMID 31315262, 2019). "In the present study, we aimed to evaluate the influence of prostatic C. acnes infection on systemic levels of IL6 and CXCL8 in prostate cancer patients." (PMID 30473726, 2018). "Specifically, IL6 and CXCL8 have been extensively studied in relation to prostate cancer, and have both been proposed to play important roles in prostate cancer development and progression." (PMID 30473726, 2018). "Cytokines involved in tumor growth and metastases, interleukin 6 (IL-6) and tumor necrosis factor-α (TNF-α), are also important serum biomarkers with high prognostic value in prostate cancer patients." (PMID 29562686, 2018). "In clinical prostate cancer samples, HER2 levels significantly correlated with IL6 levels (r = 0.2446; P = 0.0288; n = 80)." (PMID 29540470, 2018). "IL-6, in turn, can induce expression of the anti-apoptotic Bcl-3 protein via STAT3 signaling, which can contribute to prostate cancer cell survival." (PMID 30158439, 2018). "Patients showed decreased overall survival when serum values of both IL-6 and TNF-α are found above the 95th percentile values of healthy controls when compared to prostate cancer patients with values below the cutoff." (PMID 29562686, 2018). "Due to a prospective study showing that TNFα and IL-6 levels correlate with the degree of disease, and PSA progression in prostate cancer patients, TNFα and IL-6 are currently suggested as additional markers that reflect the activity level of this disease." (PMID 29946544, 2018). "In this review, we focus on two immune-related cytokines, interleukin-6 (IL-6) and receptor activator of nuclear factor kappa-B ligand (RANKL), that are expressed in the TME of prostate cancer." (PMID 28292326, 2017). "Pro-inflammatory markers such as IL-6, IL-8, CRP and TNF-α have shown to be elevated beyond normal levels in both breast and prostate cancer patients experiencing CRF." (PMID 28895922, 2017). "A human-mouse chimeric monoclonal neutralizing IL-6 antibody (siltuximab, also known as CNTO 328) has been evaluated in a phase II study in men with advanced castration-resistant prostate cancer, with PSA response rate being the primary endpoint." (PMID 28292326, 2017). "IL-6 increased circulating CD11b+CD14+HLA−DR− cells in squamous carcinoma of the esophagus and prostate cancer." (PMID 29326716, 2017). "For example, it was shown to function through being regulated by inflammatory cytokines (IL-6, CCR9 and TLR3) during apoptosis, and involve in the pathogenesis of prostate cancer." (PMID 28545028, 2017). "However, whether and how IL-6 may play a role in prostate cancer risk and development is not well defined." (PMID 28077171, 2017). "Our study demonstrates the pro-proliferative role of the oncogene IKKε in castrate-resistant prostate cancer cell lines, involving the phosphorylation and nuclear translocation of C/EBP-β that initiates IL-6 gene expression." (PMID 27577074, 2017).
prostate carcinoma (continued). "GA also presented anti-proliferative effects in leukemia and human ovarian cancer cell lines, and was shown to target prostate cancer cells via an anti-inflammatory pathway through downregulation of HMGB1, IL-6 and IL-8." (PMID 28415753, 2017). "PC3-DR cells achieve EMT as shown by cell morphology, EMT markers, increased cell invasion and secretion of interleukin-6 (IL6), a marker of prostate cancer progression." (PMID 27542265, 2016). "In this study, we evaluated the role of IL-6 in PDCD4 gene expression and how the microRNA miR-21 regulates this process in prostate cancer cell lines PC-3 and LNCaP." (PMID 26252635, 2015). "In prostate cancer PCA cells, IL-6 expression resulted in the induction of autophagy, with the autophagy pathway required for IL-6-induced neuroendocrine differentiation and chemoresistance of prostate cancer cells." (PMID 25590298, 2015). "In both LNCaP and PC3 cell variants higher levels of TLR9 expression and activation (by CpG ODN stimulation) correlated with increased mRNA and protein levels of IL-6, an important STAT3 activator and a contributor to prostate cancer progression." (PMID 26046794, 2015). "Recent reports demonstrated synergism between IL-6/STAT3 and PI3K/Akt or Src pathways in promoting prostate cancer aggressiveness and progression." (PMID 26046794, 2015). "DACH1 mRNA expression was reduced in metastatic human prostate cancer and DACH1 abundance was inversely correlated with IL-6 and IL-8." (PMID 26682253, 2015). "The prediction implied that these upstream genes play important roles in the motility, invasion, and metastasis of prostate cancer cell via ERK1/2, MAPK/JNK, PI3K, IL-6, IL-8." (PMID 26603105, 2015). "Secretion of IL-6 is dramatically decreased in prostate cancer cells upon ANXA2 knockdown, while overexpression of naive ANXA2 increases IL-6 secretion." (PMID 25611381, 2015). "The most promising general cancer markers for prostate cancer detection are transforming growth factor-β1 (TGF-β1) and interleukin-6 (IL-6)." (PMID 24877145, 2014). "Previous studies have demonstrated that NE upregulates VEGF, IL-8, IL-6 and MMP expression levels in some kinds of tumor cells in vitro such as melanoma, breast cancer, colon cancer, prostate cancer, ovary cancer, pancreatic cancer and nasopharynx cancer." (PMID 24555849, 2014). "Heat shock protein 27 (Hsp27) induces IL-6 dependent and independent EMT in prostate cancer by promoting phosphorylation and nuclear translocation of STAT3, making STAT3 to bind to the Twist promoter, and activating Twist function." (PMID 24618337, 2014). "In many cancers, like breast and prostate cancers, tumor-produced growth factors or cytokines like PTHrP, RANKL, and IL-6 play important roles in bone osteolysis." (PMID 24587095, 2014). "ANXA2 is required for the growth of prostate cancer and acts through the MAPK pathway or by upregulating IL-6 secretion." (PMID 24591759, 2014). "Treatment with either specific IL-6 antibody or a specific pSTAT3 inhibitor (LLL12), leads to a reduced colony-forming capacity of the stem-like cells from a high-grade clinical prostate cancer sample." (PMID 24618337, 2014). "IL-6 and STAT3 overexpression were seen in prostate cancer and blockade of STAT3 suppressed clonogeneity in stem cell-like cells in high grade prostate cancer patients." (PMID 24743778, 2014). "We reported previously that overexpressed IL-6 and activated STAT3 signaling are critical for aggressive tumor behavior and the transition of HR prostate cancer." (PMID 23806095, 2013). "The gene list contains inflammatory genes such as IL-6, IL-8, IL1β and COX-2, which have extensive connections to prostate cancer." (PMID 23342084, 2013). "IL6 and IL8 are of particular interest because of the rich literature concerning these interleukins and prostate cancer." (PMID 23342084, 2013). "However, the role of IL-6 in the radiation response of prostate cancer remains unclear." (PMID 23806095, 2013).
prostate carcinoma (continued). "HR prostate cancer (LNCaP-HR and TRAMP-HR) had higher levels of IL-6, more activated STAT3 and AR compared to hormone sensitive prostate cancer cells (LNCaP and TRAMP-C1) shown in our previous and the present study." (PMID 23806095, 2013). "In a pilot study we investigated the influence of a 1408 km bicycle tour on Testosterone, Interleukin 6 and PSA levels in prostate cancer patients." (PMID 23731674, 2013). "Egr1 and Egr3 bind to similar sequence motifs on promoters and it is therefore unsurprising that they share a set of target genes such as IL6 and IL8, which we have now validated as direct targets for Egr3 in prostate cancer cells." (PMID 23342084, 2013). "We conclude that IL6 and IL8, identified as Egr3 potential target genes using in silico analysis, are indeed regulated by Egr3 in prostate cancer cells." (PMID 23342084, 2013). "Studies have shown that IL6 treatment enhanced cell proliferation in PC-3 and DU145 androgen-independent prostate-carcinoma cells lines." (PMID 23762858, 2013). "Thus the IL-6 level might be significant predictor of the radiation response in prostate cancer." (PMID 23806095, 2013). "Here, we have shown that hypoxia leads to increased expression of VEGF, IL-6, and CSC marker genes such as Nanog, Oct4 and EZH2, and also increased the expression of miR-21, an oncogenic miRNA, in prostate cancer (PCa) cells (PC-3 and LNCaP)." (PMID 22952749, 2012). "ALDH+ subpopulations were detected and isolated from the human prostate cancer cell lines DU145 and long-term IL-6 stimulated LNCaP cells using ALDEFLUOR® assay and flow cytometry." (PMID 21779382, 2011). "It was reported that serum level of interleukin-6 (IL-6) was elevated in NPC and prostate cancer patients." (PMID 20964870, 2010). "The authors suggested a possible cross talk between PSMA, IL-6 and RANTES chemokine and its implication in cell proliferation and cell survival in prostate cancer cells." (PMID 21189143, 2010). "The upregulation of IL-6 by TGF-β1 has been described in other cell types including human fibroblasts, osteoblasts, prostate cancer cells, and retinal pigmented epithelial cells." (PMID 19209241, 2009). "We report elevated serum levels of the cytokines IL-6 and TNF-α in patients with prostate cancer as compared with controls." (PMID 15150588, 2004). "IL-6 and TNF-α, two cytokines with multiple and overlapping biological properties, are involved in prostate cancer development." (PMID 15150588, 2004). "In this study, we measured the serum levels of IL-6 and TNF-α in prostate cancer patients, using a highly sensitive ELISA kit, in an attempt to define their association with clinicopathological features and clinical outcome." (PMID 15150588, 2004). "The aim of the present study was to examine the relationship between interleukin-6 and C-reactive protein in patients with benign disease (BPH) and in prostate cancer." (PMID 15505624, 2004). "Such crosstalk interactions among different signal transduction pathways have been documented recently between IL-6 and EGF pathways in prostate cancer cells." (PMID 12671705, 2003). "Subsequently, PPI network analysis was conducted on these targets using the STRING database, which suggested that genes such as AKT1, TNF, IL6, STAT3, and CTNNB1 might be key targets for Osthole in the treatment of prostate cancer." (PMID 40978029, 2025). "For instance, Siltuximab, an IL-6 antagonist, has demonstrated favourable tolerability in clinical trials but has not shown significant survival benefits in patients with prostate cancer, clear cell renal cancer, or other solid tumours such as ovarian cancer." (PMID 39858048, 2025). "We aimed to investigate the effects of a 6-month HOET on interleukin (IL)−1 beta (IL-1ß), IL-2, IL-6, IL-10, IL-12p70, tumor necrosis factor-alpha (TNF-α), interferon-gamma (IFN-γ), and the mGPS of colorectal, breast, and prostate cancer patients after surgery." (PMID 40498221, 2025).